TIMP3 (TIMP metallopeptidase inhibitor 3)
Diseases named in the same sentence as TIMP3 in open-access papers (continued):
Sharing a sentence is not in itself a finding about the gene and the disease.
tumor (continued). "TIMP3 is a naturally occurring angiogenesis inhibitor that suppresses the growth of malignancies by limiting the number of vessels in the vascular bed of the tumor." (PMID 41009435, 2025). "For the TIMP3 promoter, a dose-dependent decrease in methylation of 49% (p < 0.01) and 68.5% (p < 0.001) was observed following seaberry treatment, relative to untreated tumor samples." (PMID 40371330, 2025). "Furthermore, miR-21 is upregulated in various cancers, including EC, where it targets tumor suppressor genes such as PDCD4 and TIMP3, resulting in enhanced tumor cell proliferation and survival." (PMID 39944625, 2025). "Hence, we examined the relationship between TIMP3 and TC immunity, specifically focusing on tumor immune cell infiltration, immunity regulators, chemokines, and their receptors." (PMID 38410497, 2024). "Furthermore, they also found that TIMP3 was highly enriched in metastatic tissues compared to that in primary tumours." (PMID 38542164, 2024). "However, by upregulating tissue inhibitor of metalloproteinase 3 (TIMP3), a well-known tumor suppressor that functions by sponging miR-17-3p and miR-181b-5p, hsa_circ_0001445 (cSMARCA5) suppresses the migration and proliferation of HCC cells." (PMID 39120276, 2024). "This indicates that TIMP3 might play a regulatory role in the immune response of tumor cells by coordinating the expression of these immunomodulators." (PMID 38410497, 2024). "Studies have also shown that TIMP3 might work as a tumor suppressor in TC by inhibiting angiogenesis and macrophage infiltration." (PMID 38410497, 2024). "EPS exerts its anti-inflammatory effects by downregulating the expression of VEGF in tumor cells, upregulating the expression of the anti-angiogenic factor tissue inhibitor of metalloproteinases-3 (TIMP-3), downregulating pro-inflammatory factors, and upregulating anti-inflammatory factors." (PMID 39710789, 2024). "We chose these MMPs and TIMP-3 for their importance in tumor progression." (PMID 37108185, 2023). "Thus, ECs from the tumor zone from prostatectomy showed higher expressions of MMPs and TIMP-3 compared to ECs of the corresponding zone from the benign biopsy." (PMID 37108185, 2023). "TIMP3 is downregulated in most cancers and plays a tumor suppressor role in many cancer processes." (PMID 36768435, 2023). "In addition, TIMP3 overexpression in hormone receptor-positive BC cells reduces tumor growth and invasion while inducing apoptosis in ER+ tumor cells." (PMID 38069080, 2023). "Moreover, the character of TIMP-3 that can serve as tumor progression predictor let TIMP-3 own the potentiality to become a target for cancer therapy." (PMID 36860920, 2023). "Importantly, some the genes upregulated upon ZNF714 knockdown (PCDH20, STRA6, ARNT2, TIMP3) were previously shown to function as tumor suppressors." (PMID 37958512, 2023). "TIMP3 belongs to the tissue inhibitors of metalloproteinases (MMPs) that regulate the pericellular proteolysis of a vast range of matrix and cell surface proteins, generating simultaneous effects on the tumor architecture and cell signaling." (PMID 37511403, 2023). "In premenopausal patients (n = 11), six genes were statistically significantly down-regulated in tumour tissue compared to tumour-adjacent tissue: TIMP3 (13.1-fold), ENPP2 (11.4-fold), FGF2 (7.6-fold), CXCL12 (7.5-fold), TIMP2 (5.2-fold), and PDGFRB (4.9-fold change)." (PMID 37509322, 2023). "After dividing the UCC population into the non-smoker and smoker, the presence of muscle invasive tumor type was significantly correlated to the TIMP-3 SNP rs9619311 TC + CC variant in the non-smoker subgroup (OR: 2.149, 95% CI: 1.143-4.039, P = 0.016)." (PMID 36860920, 2023). "Concerning the subgroup analyses in the current study dependent on the existence of tobacco consumption, the UCC individuals who never smoke would experience higher tumor stage of the TIMP-3 SNP rs9619311 variant was existed." (PMID 36860920, 2023).
tumor (continued). "Similarly, the literature studies that are related to prostate cancer confirmed that TIMP3 is a tumor suppressor gene that is frequently downregulated in prostate cancer, and its overexpression can inhibit tumor cell growth and induce apoptosis." (PMID 36612628, 2022). "In fact, TIMP3 was a widely studied tumour suppressor in many cancer types." (PMID 33560588, 2022). "Regarding CNAs, the main affected genes in this series of primary MN that recurred are located on chromosomes 22q (TIMP3), 1p (TP73), 6q (ESR1 and PARK2), and 18q (BCL2); the association among these chromosomes’ alterations and tumor recurrence has been previously demonstrated." (PMID 36011000, 2022). "Moreover, the overexpression of miR‐181b significantly repressed the expression of anti‐tumour genes, such as TIMP3 which regulates the EMT process." (PMID 33560588, 2022). "Similarly, the current study also confirmed that ALKBH5 knockdown increased mRNA stability, which increased TIMP3 protein expression and acted as a tumor suppressor in A549 cells." (PMID 35318440, 2022). "When compared to normal skin samples, TIMP-3 appeared down-regulated in most of tumor samples." (PMID 36713871, 2022). "TIMP3 regulates cell death, angiogenesis, and tumor cell invasion." (PMID 36555545, 2022). "The downregulation of TIMP-3 expression has been observed in several tumours, thus suggesting that it plays a tumour-suppressive role, and accordingly, it has been demonstrated that TIMP-3 expression induces apoptosis in cancer cell lines and reduces the invasiveness of cancer cells in vitro." (PMID 36013323, 2022). "MiR-21 by inhibition of anti-angiogenic factors such as tissue inhibitor of metalloproteinase-3 (TIMP3) in tumor-infiltrating myeloid cells’ (TIMs) could promote metastatic tumor angiogenesis and proliferation through modulating the tumor microenvironment." (PMID 35499045, 2022). "TIMP3 is an ADAMs and MMPs inhibitor with tumor suppressor activity." (PMID 34503180, 2021). "TIMP3 is an accepted tumor suppressor gene and can inhibit tumor invasion and metastasis." (PMID 33808751, 2021). "Overexpression of TIMP-1, TIMP-2, and TIMP-3 reduces tumor growth." (PMID 35201460, 2021). "Based on the results presented above, we speculated that circSMARCA5 could play tumor-suppressive effects via miR-181b-5p-regulated and/or miR-17-3p-regulated TIMP3." (PMID 34390329, 2021). "Additionally, miR-21 can enhance tumor metastasis and angiogenesis by inhibiting anti-angiogenic genes such as TIMP3, COl4a2, and Spry1 in tumor-infiltrating myeloid cells." (PMID 34778378, 2021). "The pooled ORs showed a significant association between specific tumor-related genes and HNC risk: p16 (3.75; 95% CI = 2.51–5.60), MGMT (5.72; 95% CI = 3.00–10.91), DAPK (5.34; 95% CI = 2.18–13.10), TIMP3 (3.42; 95% CI = 1.99–5.88), and RASSF1A (7.69; 95% CI = 3.88–15.23)." (PMID 34206840, 2021). "TIMP3 frequently leads to a poor prognosis because of silencing in tumours." (PMID 34781885, 2021). "In addition to being a marker for predicting cancer progression, TIMP3 can also be used as a therapeutic target for cancer and a marker of tumour sensitivity to drugs." (PMID 34781885, 2021). "Previous studies indicated that TIMP3 as a tumor suppressor could modulate tumor migration, invasion, and tumorigenicity." (PMID 33750388, 2021). "The functional investigations were quite definitive, however, with the ablation of TIMP-3 in mice leading to enhanced tumor growth and invasion and enforced expression decreasing the proliferation, survival, migration and invasion, as well as increasing apoptosis and chemosensitivity." (PMID 33808504, 2021).
tumor (continued). "Of note, the expression of previously well-established in vitro targets of miR-21 having tumor-suppressive activity, i.e., Ppara, Pdcd4, Timp3, Spry2, Pten, and Hbp1, was unchanged with miR-21 deficiency in vivo in mice again highlighting a cell/organ context-dependent action of miR-21." (PMID 34638467, 2021). "Thus, our finding about FKBP51 mediated autophagic degradation of TIMP3 provides not only novel insight into autophagy regulation in tumor metastasis but also an attempt to redefine the regulatory roles of FKBP51 in tumor cell autophagy." (PMID 34599146, 2021). "In the past decade, several reports showed that TIMP-3 acts as a tumor suppressor in cancer cells." (PMID 33126605, 2020). "TIMP3 is located on 22q12.3 and codes for a protein that can specifically inhibit matrix metalloproteinases (MMPs) via covalent binding to the active site of the enzymes and reduces the invasiveness of tumor cells." (PMID 33014773, 2020). "TIMP3 is considered a tumor suppressor in different cancer types." (PMID 32896063, 2020). "We then assessed MMPs and TIMP3 expression in tumors and adjacent non-tumor colon tissue in CRC patients, MMP12 (P = 0.001), MMP9 (P = 0.0006) and TIMP3 (P = 0.0421) mRNA expression was significantly increased in tumors tissue compared to adjacent non-tumor tissue from CRC patients." (PMID 32171282, 2020). "In summary, we report in this study that circFNDC3B/miR‐937‐5p/TIMP3 axis governs CRC tumor progression, angiogenesis and liver metastasis and demonstrate that circFNDC3B induces TIMP3 to suppress angiogenesis to inhibit CRC progression by targeting miR‐937‐5p." (PMID 32896063, 2020). "Moreover, the TIMP-3, MMPs and tumor growth factors present in the ECM use heparan sulfate proteoglycans as docking sites." (PMID 33167307, 2020). "Therefore, detailed mechanisms of TIMP3 regulating early tumor development should be further elucidated." (PMID 31588243, 2019). "This highlights a level of redundancy between TIMP2 and TIMP3 activities and raises the intriguing idea that combinatorial administration of TIMP2 and TIMP3 to tumors may augment previous anti-tumor findings observed with TIMP2." (PMID 31882975, 2019). "In addition to the anti-tumor and anti-metastasis capability, MPT0B390 can also induce TIMP3 expression in endothelial cells to inhibit tumor angiogenesis." (PMID 31588243, 2019). "Different results for the effect of TIMP3 expression on tumor cell growth have been reported." (PMID 31624299, 2019). "Moreover, TIMP3 has been reported to inhibit tumor growth, angiogenesis, invasion, and metastasis and promote apoptosis." (PMID 30988064, 2019). "In addition, TIMP3 expression was elevated in certain tumor areas in lung tissues treated with MPT0B390." (PMID 31588243, 2019). "TIMP3 is a dual inhibitor of MMPs and ADAM in the tumor microenvironment, and the lack of TIMP3 has been associated with angiogenesis and cancer cell invasion." (PMID 31835496, 2019). "TIMP3 has tumor-suppressive functions in several human malignancies." (PMID 29731768, 2018). "Another example is cSMARCA5, which could promote the expression of TIMP3, a well-known tumor suppressor, by sponging miR-17-3p and miR-181b-5p35." (PMID 30361504, 2018). "TIMP3 acts as a tumor suppressor to inhibit tumor growth, invasion, and angiogenesis." (PMID 29731768, 2018). "This led to the identification of 30 miRNA-mRNA interaction pairs involving known tumor suppressor targets of miR-21a-5p (Reck, Timp3 and Tgbr3) and miR-31-5p (Lats2 and Dmd) as well as oncogenic targets of miR-143-3p (Kras), miR-145-5p (Klf5, Kras) and miR-1195-5p (Met)." (PMID 30412601, 2018). "TIMP3 is related to genes regulating apoptosis, which have been proposed as tumor suppressors." (PMID 29731768, 2018). "TIMP-3 also decreases tumour growth in xenograft models indicating its potential as a therapeutic." (PMID 29617412, 2018). "Some authors emphasize a unique role of TIMP3 as a tumor suppressor." (PMID 29304854, 2018).
tumor (continued). "TIMP3 exhibits the ability to inhibit tumor angiogenesis, invasion, and metastasis." (PMID 29304854, 2018). "B16F10 tumor metastasis was higher in lungs of TIMP-3 knockout mice." (PMID 29467412, 2018). "Interestingly TIMP3, an inhibitor of matrix metalloproteinases, was also found to be downregulated in these tumours." (PMID 28886030, 2017). "TIMP3 suppresses tumor inactivation in cancer by mechanisms of invasion and angiogenesis." (PMID 29236770, 2017). "In addition, the TIMP3 methylation levels in tumour tissues were able to predict the formation of secondary tumours." (PMID 27663357, 2016). "We noted however that compound loss of Timp3 and Tnf (PyMT Timp3−⁄−Tnf−⁄−) did not further this suppression, suggesting overlapping functions of Timp3 and Tnf during PyMT tumor initiation." (PMID 25807548, 2015). "Other groups have shown that the overexpression of Timp3 can protect against tumorigenesis by stabilizing TNF family death receptors on the surface of tumor cells via the blocking of receptor shedding and increasing their sensitivity to extracellular death signals." (PMID 25807548, 2015). "Thus, we have analyzed the promoter methylation of RASSF1A and TIMP3 genes in mammary gland and tumor at 246 days of age, finding a significant increase in both tissues in the corn oil-enriched diet groups, especially in HCO." (PMID 26401660, 2015). "Further, Timp3 deficiency specifically within mammary stroma is sufficient for delayed tumor onset, although the loss of Timp3 does not alter the mammary immune composition." (PMID 25807548, 2015). "The kinetics of tumor progression were decelerated in the PyMT Timp3−⁄− cohort." (PMID 25807548, 2015). "Among the TIMPs, TIMP-3 has been identified as a unique tumor suppressor and is the only member of the TIMPs that could tightly bind to the extracellular matrix." (PMID 25171061, 2014). "Finally, we show that this TIMP-3 peptide has potent inhibitory effects on murine tumour angiogenesis and growth as well as inflammatory arthritis in vivo." (PMID 24129822, 2014). "TIMP-3 has been demonstrated to inhibit tumor angiogenesis, invasion, and metastasis." (PMID 25171061, 2014). "TIMP-3, the only member of the TIMPs that can tightly bind to the extracellular matrix, has been identified as a unique tumor suppressor that demonstrates the ability to inhibit tumor angiogenesis, invasion, and metastasis." (PMID 25171061, 2014). "Importantly, MPT0G013 exhibited antiangiogenic activities in in vivo Matrigel plug assays, inhibited tumor growth and up-regulated TIMP3 and p21 proteins in HCT116 mouse xenograft models." (PMID 25226613, 2014). "Furthermore, Zhang and co-workers demonstrated that miR-221/222 knockdown decreased the invasion capability and tumor growth and up-regulated the expression of suppressor gene tissue inhibitor metallopeptidase 3 (TIMP3)." (PMID 25909813, 2014). "An increased expression of p16, p15 and TIMP3 in BMI1-silenced tumor cells was observed." (PMID 23671559, 2013). "The role of TIMP3 as a putative tumor suppressor is confirmed by the fact that TIMP3 is silenced in various types of human cancers and malignant cell lines, suggesting that the silencing of TIMP3 in tumor cells is an important event during tumor development." (PMID 23894681, 2013). "Evidence from several studies shows that overexpression of TIMP3 inhibits tumor growth in vivo." (PMID 23894681, 2013). "A close association between BRAF mutation and aberrant methylation of several tumor-suppressor genes in PTC, including the genes for tissue inhibitor of matrix metalloproteinase-3 (TIMP3), death-associated protein kinase (DAPK), and retinoic acid receptor β2 (RARβ2) has been reported." (PMID 24868250, 2013). "Gene therapy by retroviral vector for cell-mediated in vivo delivery of TIMP-3 could suppress tumor-induced angiogenesis and tumor growth." (PMID 21876694, 2012).
tumor (continued). "In addition, knockdown of miR-221/222 increased TIMP3 expression and considerably inhibited tumor growth in a xenograft model." (PMID 22681957, 2012). "Furthermore, knockdown of miR-221/222 decreased invasion capability, reduced tumor growth and up-regulated the expression of the target, TIMP3, whereas ectopic expression of miR-221/222 exhibited the opposite effects." (PMID 22681957, 2012). "Indeed, they enhance tumorigenicity in non-small cell lung cancer (NSCLC) and hepatocarcinoma cells (HCC) by targeting PTEN and TIMP3 tumor suppressors; in turn, they are activated by c-MET through the AP-1 transcription complex." (PMID 21711453, 2011). "At the same confidence interval, TIMP-1 and TIMP-3 also correlated with increasing tumour grade." (PMID 16465195, 2006). "This methylation-associated silencing of TIMP-3 is tumour-specific, and associated with lack of TIMP-3 protein expression in primary cancers." (PMID 15467768, 2004). "However, the relationship between TIMP-3 expression and clinical features (tumour invasiveness, metastasis and prognosis) in patients with ESCC is not known." (PMID 15467768, 2004). "Thus, TIMP3 may affect prognosis by controlling TAMs in the tumor microenvironment, which could potentially extend the lives of patients." (PMID 41009435, 2025). "Moreover, the muscle invasive tumor type was significantly correlated to the TIMP-3 SNP rs9619311 TC + CC variant in the non-smoker subgroup (OR: 2.149, 95% CI: 1.143-4.039, P = 0.016)." (PMID 36860920, 2023). "Moreover, the TIMP-3 SNP rs9619311 variant is correlated to higher tumor stage in the non-smoker population who diagnosed with UCC." (PMID 36860920, 2023). "Furthermore, Xing M demonstrated that activation of MAPK signaling pathway resulted in upregulation of tumor-promoting genes (e.g. VEGFA, MET, HIF1A, UPA, UPAR, TGFB1, and TSP1) as well as downregulation of tumor suppression and thyroid genes (e.g. TIMP3, SLC5A8, DAPK1, NIS, TSHR, and TPO)." (PMID 35600399, 2022). "Other examples of tumor suppressor genes described as mutated in OS include the β-catenin regulatory protein APC (Adenomatous polyposis coli), the metalloproteinase inhibitor TIMP3 (Metalloproteinase inhibitor 3) and the Wnt pathway inhibitor WIF-1 (Wnt inhibitory factor 1)." (PMID 35884563, 2022). "Additionally, the overexpression of TIMP3 may reduce vascular density, promote apoptosis and inhibit malignant behaviors, including migration, invasion, and tumor growth of CRC cells." (PMID 35487956, 2022). "Moreover, analyses of a miRNA database and mRNA-sequencing data of the mutant UQCRB-expressing cell lines revealed that TIMP3, a tumor suppressor, could be a target of miR-4435." (PMID 32071343, 2020). "Tissue inhibitor of metalloproteinase-3 (TIMP3), one of four members of a protein family that were originally classified based on their ability to inhibit MMPs27,28, is a naturally occurring inhibitor of angiogenesis that limits vessel density in vascular bed of tumors and curtails tumor growth." (PMID 31757977, 2019). "Also, we found significant promoter hypermethylation in high tumor grades of OC for p16INK4a and RASSF1A and of OPC for p16INK4a, RASSF1A, and TIMP3, suggesting the correlation between promoter hypermethylation of tumor-related genes and poor prognosis of OC and OPC." (PMID 31013839, 2019). "Moreover, TIMP-3 suppresses tumor angiogenesis in MMP-2-downregulated lung cancer." (PMID 29467412, 2018). "Conversely, decreased TIMP3 expression has been observed in a variety of malignancies and has been correlated with aggressiveness in cancers arising in the thyroid, breast, prostate and lung, which supports a role for TIMP3 as a tumor suppressor via its ability to inhibit MMPs." (PMID 25587717, 2015).